CD69 (CD69 molecule)
Diseases named in the same sentence as CD69 in open-access papers (continued):
Sharing a sentence is not in itself a finding about the gene and the disease.
Kawasaki disease (1 paper, 2021). A rare inflammatory disease characterized by an acute febrile, systemic, self-limiting, medium-vessel vasculitis primarily affecting children. "The expression of CD25 and CD69 on lymphocytes was higher in patients with Kawasaki disease than in healthy controls." (PMID 33622252, 2021). "Flow cytometry was used to detect the expression of CD25 and CD69 on the surface of activated peripheral lymphocytes in acute-phase Kawasaki disease." (PMID 33622252, 2021). "The expression of activin type IIA receptors on CD8+ T cells and CD19+ B cells was increased in acute-phase Kawasaki disease and decreased following treatment with activin A. Activin A suppressed the expression of CD25 and CD69 on CD8+ T cells and the expression of CD69 on CD19+ B cells." (PMID 33622252, 2021).
liver cirrhosis (1 paper, 2020). "A number of co-stimulatory molecules, namely CD40L, OX-40, GITR, and TIM-1 were significantly upregulated on both effector and regulatory CD4+ T cells in patients with liver cirrhosis compared to healthy controls, as well as the T cell activation markers CD69 and CD38." (PMID 33574809, 2020).
lymphocytic leukemia (1 paper, 2024). "In lymphocytic leukemia cell lines, these alterations result in changes in tumor infiltration of NK cells, macrophages, CD4+ T cells, and CD8+ T cells, and increased CD69 expression on both CD4+ and CD8+ T cells." (PMID 39436703, 2024).
lymphoid tumor (1 paper, 2016). "In agreement with this, tumor cells derived from lymphoid tumor niches harbored higher CD69 expression and were less sensitive to bendamustine than their peripheral blood counterparts." (PMID 26701728, 2016).
nephritis (1 paper, 2024). Inflammation of renal tissue. "Interestingly, relevant subpopulations of T cells also expressed the TRM associated markers CD69 and/or CD103 in both AIN and ICI-associated nephritis." (PMID 38961265, 2024). "A translational aspect of our model is strongly supported by the identification of comparable CD69+ and CD103+ T cell subpopulations in kidney samples from patients with various types of auto-immune nephritis, including AIN or ICI-related nephritis." (PMID 38961265, 2024).
neuroendocrine neoplasm (1 paper, 2023). Endocrine tumors, also referred to as neuroendocrine tumors (NETs), are defined by a common phenotype which is characterized by the expression of general markers (neuron specific enolase, chromogranin, synaptophysin) and hormone secretion products. "A previous report found that neuroendocrine neoplasm patients with lower pre-treatment activation state (CD69 expression) of naïve T cells and NK cells were associated with longer progression-free survival after anti-PD-1 immunotherapy." (PMID 37180581, 2023). "The recent research about neuroendocrine neoplasms found a negative correlation between progression-free survival after anti-PD-1 immunotherapy and expression of the CD69 activation marker on naïve T and NK cells in pre-treatment peripheral blood samples." (PMID 37180581, 2023).
nonalcoholic steatohepatitis (1 paper, 2022). "Interestingly, a recent study revealed that CD69+CD103-CD8+ TRM cell may perform a protective role in resolving liver fibrosis of nonalcoholic steatohepatitis (NASH)." (PMID 36172356, 2022).
ovarian endometriosis (1 paper, 2006). A non-neoplastic disorder characterized by the growth of endometrial tissue in the ovaries. "The results of statistical analysis of metallothionein (MT), RCAS1, CD68, CD56, CD16, CD25 and CD69 expression in ovarian endometriosis, scar endometriomas and secretory endometrium performed by Kruskal-Wallis analysis of variance (ANOVA) test." (PMID 16907986, 2006).
pancreatitis (1 paper, 2023). Inflammation of the pancreas. "The cell surface expression of T-cell activation markers CD25 and CD69 were significantly increased in Irak3−/− 8 h after onset of pancreatitis." (PMID 37402858, 2023). "We observed in severe pancreatitis an increased T-cell activation marked by the elevated cell surface expression of CD25 and CD69 on T-helper cells." (PMID 37402858, 2023).
pars planitis (1 paper, 2016). An inflammatory disorder of the cilliary body in the uvea that affects healthy, younger individuals who are often asymptomatic. "The exact cause of pars planitis remains unknown, but CD4+ T cells that express an activation marker CD69 (an early activation marker) in either peripheral blood or in the aqueous humor are found, respectively, in patients with pars planitis and with idiopathic uveitis." (PMID 26438050, 2016).
Peritoneal Fibrosis (1 paper, 2024). Disorder characterized by a wide range of structural changes in PERITONEUM, resulting from fibrogenic or inflammatory processes. "CD69−/− transgenic mice showed increased numbers of Th17 cells, higher expression of IL-17, and enhanced peritoneal fibrosis compared to wild-type mice in a PDF-treated model." (PMID 39201294, 2024). "In addition, IL-17 blockade alleviated this process, suggesting that CD69 controls peritoneal fibrosis by regulating Th17 responses." (PMID 39201294, 2024).
peritonitis (1 paper, 2009). Inflammation of the peritoneum (tissue that lines the abdominal wall and covers most of the organs in the abdomen). "Peritoneal Vγ9/Vδ2 T cell frequencies and CD69 expression levels in HMB-PP+ peritonitis patients were consistently higher than in the peripheral blood of the same patients (data not shown), implying local recruitment/proliferation and activation in the peritoneal cavity." (PMID 19229322, 2009).
pertussis (1 paper, 2011). A contagious bacterial respiratory infection caused by Bordetella pertussis. "The vaccination also induced a significant increase in CD8+CD69+ T cells responsive to pertussis antigens." (PMID 21408149, 2011). "Four weeks after the adolescent aP vaccination CD8+CD69+ activated T cells were augmented when PBMC were stimulated with all four tested pertussis antigens, whereas CD4+CD69+ T cells were decreased in FHA, PRN and FIM stimulated cultures." (PMID 21408149, 2011).
pharyngitis (1 paper, 2022). Inflammation of the throat most often caused by viral and bacterial infections. "To further elucidate functional immune responses during acute S. pyogenes pharyngitis, we analysed cells for CD69 expression (a marker of activation), CXCR3 (a marker of migration) and intracellular perforin and granzyme-B expression (cytotoxic proteins involved in cell lysis)." (PMID 35140232, 2022). "In contrast, CD4+ and CD8+ T cells did not upregulate CD69 expression during acute pharyngitis." (PMID 35140232, 2022).
pituitary cancer (1 paper, 2010). A primary or metastatic malignant neoplasm affecting the pituitary gland. "Axolotls uniquely up regulated genes that are associated with vertebrate brain development and mammalian brain pathologies, including ctss and aging, ogn and pituitary cancer, and cd69 and Alzheimers." (PMID 20584293, 2010).
renal cell carcinoma (1 paper, 2023). "In addition, it has been reported that anti-CD69 antibodies can enhance the anti-tumor effects against the murine renal cell carcinoma (Renca) cell line by promoting T cell proliferation, IL-2 expression, and cytotoxicity." (PMID 37880277, 2023).
Rotavirus infection (1 paper, 2025). Infection with any of the rotaviruses. "Rotavirus infection results in rapid and profound B cell activation characterized by increased numbers of CD19+/CD69+ B cells in the Peyer's patches of mice within 48 hours of viral exposure." (PMID 40304491, 2025).
schistosomiasis (1 paper, 2019). An infectious disease caused by parasitic trematodes of the genus Schistosoma that colonize human blood vessels and release eggs that can cause granulomatous reactions leading to acute (swimmer's itch or acute schistosomiasis syndrome) or chronic disease. "Praziquantel administration, in the absence of schistosomiasis, did not tend to reduce HIV entry into blood-derived CD4+ T cells or alter systemic CD69+ CD4+ T cell frequency." (PMID 31127086, 2019).
skin inflammation (1 paper, 2019). "Hh also reduced expression of other genes for inflammatory signaling pathways implicated in skin inflammation including TNFR (Tnfrsf25), JAK-STAT (Jak1), and NF-κB (Trl4, Myd88, Cd69, Cd48, Irf1)." (PMID 31264977, 2019).
skin reaction (1 paper, 2022). "The baseline frequency of CD69+CD4+ T cells was higher in subjects who presented with skin reactions during benznidazole therapy than that of the uninfected group, whereas the frequency of CD69+CD8+ T cells was not different among groups." (PMID 35938810, 2022).
soft tissue sarcoma (1 paper, 2022). A malignant neoplasm arising from muscle tissue, adipose tissue, blood vessels, fibrous tissue, or other supportive tissues excluding the bones. "This fact was demonstrated when CD8+ CD69+ TILs expanded from patients with soft tissue sarcoma had more tumor-specific functional capacity due to more IFN-γ and granzyme B production." (PMID 36513720, 2022).
steatosis (1 paper, 2022). Increased lipid within the cytoplasm of cells. "In contrast, DI participants showed decreased circulating expression of the activation marker CD69 and improvements in histological steatosis grade post-intervention." (PMID 35683998, 2022).
synovitis (1 paper, 2023). Inflammation of a synovial membrane. "SLC16A3 mRNA expression positively correlated with the histological grade of synovitis (CD3, CD20, CD69 and CD138 infiltration) and the disease activity score (DAS28 ESR and CRP)." (PMID 37304267, 2023).
T-cell leukemia (1 paper, 2014). A malignant disease of the T-lymphocytes in the bone marrow, thymus, and/or blood. "It has also been shown that miR-181a repressed the expression of genes which play a role in thymocyte maturation, such as Bcl-2, CD69, and the T-cell receptor, and the members of the miR-181 family were found to be significantly overexpressed in T-cell leukemia in our study." (PMID 24955371, 2014).
triple-negative breast carcinoma (1 paper, 2025). An invasive breast carcinoma which is negative for expression of estrogen receptor (ER), progesterone receptor (PR), and human epidermal growth factor receptor 2 (HER2). "Clinical observations suggest that patients with elevated CD69 expression have increased disease-free survival compared to those with low CD69 levels, which has been observed in triple-negative breast cancer." (PMID 40725022, 2025).
tuberculous pleurisy (1 paper, 2011). "However, following stimulation with MTB-specific peptides of ESAT-6/CFP-10, CD4+CD69+ T cells from the same patients with tuberculous pleurisy expressed high levels of IFN-γ, IL-2 and TNF-α, indicating that the response was MTB-specific." (PMID 21887301, 2011).
viral hepatitis (1 paper, 2017). An acute or chronic inflammation of the liver parenchyma caused by viruses. "Cytotoxic proteins were only expressed in a small fraction of liver CD69 + CD8+ T cells in patients without viral hepatitis, however, in livers from CHB patients more CD69 + CD8+ T cells were granzyme B+." (PMID 28733665, 2017).
viral pneumonia (1 paper, 2021). Inflammation of the lung parenchyma that is caused by a viral infection. "Thus, MAIT cell CD69 expression appears to be a highly sensitive, though not necessarily disease-specific, marker of disease severity in severe viral pneumonia, likely through integration and amplification of multiple cytokine-driven signals." (PMID 34529726, 2021).
Zinc deficiency (1 paper, 2025). A deficiency of the essential metal Zinc; an essential cofactor for many enzymes. "However, zinc deficiency may be associated with reduced activation of CD56dim and CD56bright NK cells, as assessed by the expression of CD69." (PMID 40087783, 2025).
tumor (807 papers, 2006 to 2026). "This difference was particularly pronounced in tumor tissues, suggesting that a more exhausted phenotype was associated with CD69+ T cells." (PMID 40361474, 2025). "These cells were also clearly distinct from the tumor-associated CD69+IFNG+PRF1– and the dysfunctional/low cytotoxic NR4A1+ CD158a (KIR2DL1)+ CD158e (KIR3DL1)+ NK cell populations described in the other studies." (PMID 40530504, 2025). "In contrast, within tumor tissues, T cells expressing CD69, including the CD69+CD103+CD8+ population, were associated with an increased recurrence risk, whereas increased frequencies of CD69−CD4+ and CD69−CD8+ T cells were associated with better outcomes." (PMID 40361474, 2025). "Together, the data show that the loss of SPPL3 and subsequent upregulation of nsGSLs by tumor cells protect them from elimination by γδ T cells and promote CD69 upregulation by γδ T cells." (PMID 39655358, 2025). "The expression of CD69 is shown to negatively regulate the number of tumor-infiltrating T cells and is associated with CD8+ T cell exhaustion." (PMID 41369406, 2025). "Tumor-associated CD69+ perforin– NK cells were found to attract myeloid-derived suppressor cells in ICB-refractory tumors." (PMID 40530504, 2025). "In contrast, NeoTCR clonotypes in tumor more highly expressed a CD39+CD69+ terminal differentiation signature associated with poor responses (p < 0.001)." (PMID 41415427, 2025). "The percentages of infiltrating CD45+ cells, CD3+ T cells, CD8+ T cells, and CD69+ CD8+ T cells were increased in irradiated TRIM21-deficient tumours." (PMID 36797289, 2023). "Flow cytometry analyses of the tumor-associated CD3+ T lymphocytes showed significant increase in CD69 expression in response to the combined NaHCO3 and anti-PD-L1 treatment." (PMID 37894298, 2023). "Of these eight genes, four (GNAI3, PCDH7, PSEN1, TNFSF9) were highly expressed in tumor tissues and were associated with poor prognosis, while CD69, SLC11A2, and TLR2 were poorly expressed in tumor tissue and were associated with good prognosis." (PMID 36117156, 2022). "More rapid tumor cell kill was associated with more rapid T-cell activation, as illustrated by the up-regulation of CD69 in both naive and memory subsets." (PMID 36271507, 2022). "Among these, CD69 was significantly associated with all 23 cells, the vast majority positively, including anti-tumor cells and immunosuppressive cells." (PMID 36117156, 2022). "The underlying mechanisms of these tumor antigen‐induced CD4+CD69+FOXP3− Tregs in HCC need further investigation for cancer immunotherapy." (PMID 35474948, 2022). "Patient-derived NK cells showed a markedly decreased expression of CD16 and a trend of decreased expression of several other genes known to play a role in NK-mediated anti-tumor activity, including genes encoding for NKp46, CD69, CD62L, DAP10 and GZMB." (PMID 35116033, 2021). "The present study further shows that beneficial effects are likely associated with improved CD8 T cell immunity and increased tumour infiltration by tumour-specific CD103+CD69+ TRM cells." (PMID 34471106, 2021). "The expression of CD69, NKp44 and RORγT was significantly reduced in the tumor-associated ILCs, indicating possible infiltration of circulating cells into the tumor tissue." (PMID 32341343, 2020). "To further investigate the possible reasons for the reduced tumor control caused by B cell depletion, we analyzed the expression of CD69, IFN-γ and CD107a on both CD8+ and CD4+ T cell populations." (PMID 32929370, 2020). "Nevertheless, numerous studies have found a positive association between tumor CD69+CD103+T-cell infiltration and clinical outcomes, suggesting the beneficial role of this immune cell population in restricting tumor development and therapeutic responses." (PMID 32695313, 2020). "A recent report revealed that tumor- and liver-infiltrating lymphocytes express CD69 over 50%, which is a hallmark of tissue-resident lymphocytes, in HCC patients." (PMID 33379384, 2020).
tumor (continued). "On the other hand, KRAS mutated tumours were associated with decreased fractions of CD69+ Th cells, Tregs, CD69+ NK cells and CD69+ B cells." (PMID 33228141, 2020). "We found that higher percents of TRM (defined as CD69+CD103+ in IEL and tumor, and CD69+LFA1+ in liver) associated with smaller effects of IR in the numbers of parenchymal CD8+ T cells." (PMID 31477729, 2019). "CD69 expression was upregulated on both L-selectin sufficient and L-selectin deficient T cells harvested from spleen of tumor bearing mice, however it was significantly higher on F5LΔP T cells compared to F5LselKO T cells." (PMID 31249570, 2019). "In murine models, CD69 deficiency is associated with enhanced anti-tumor immunity and longer survival." (PMID 31649887, 2019). "When L-selectin sufficient and deficient cells were harvested from the spleens of non-tumor bearing mice which had undergone sub-lethal irradiation and peptide vaccination, there was a uniform increase in CD69 expression in both F5LΔP and F5LselKO T cells." (PMID 31249570, 2019). "Major differences in receptor expression were associated with activation (HLA-DR, CD69), tumor recognition (NCRs and NKp80), and immune regulation (TIM-3 and LAG-3)." (PMID 31695700, 2019). "In cancer, HIF-1 activation is associated with expression of CD69 (a marker of activated T cells) on cytotoxic T lymphocytes (CTLs) in hypoxic regions of tumour, suggesting a pro-tumour killing role for HIF-1α." (PMID 30301842, 2018). "We demonstrate that IL-15 expression in the tumour-bearing brains of EE mice is associated with in situ accumulation of activated CD45+/CD69+ leukocytes, and specifically of NK cells, that are markedly increased in comparison with SE mice." (PMID 25818172, 2015). "Interestingly, CD69, an additional marker of tissue retention that is also a classic early activation marker, was expressed by both tumor-associated NK-cell subsets, although trNK cells showed significantly higher CD69 frequencies in both patient groups." (PMID 40607422, 2025). "In addition, KLF2, a transcription factor which is downregulated in TRM to promote the formation of CD69 was found it underlies the regeneration and persistence of a subpopulation of miRNA -125Highbreast tumor cells via an epigenetic way." (PMID 40895552, 2025). "Therefore, in the present study, we aimed to investigate the distinct characteristics of CD69+ and CD69− T cells of the liver and tumor and their associations with clinical or histopathological parameters." (PMID 40361474, 2025). "However, studies have implicated a role for CD69 in promoting exhaustion in tumour-infiltrating T cells perhaps as a result of prolonged T cell activation promoted by CD69 signalling in the T cells." (PMID 36445478, 2023). "However, deficiency in CD69 in animal models or targeting CD69 showed an attenuated tumor growth and improved anti-tumor immunity." (PMID 37901220, 2023). "Notably, some researchers also found that CD69 deficient intratumoral T cells showed a decreased proportion of exhaustion in 4T1 tumor-bearing mice." (PMID 37180581, 2023). "Interestingly, a high level of P. micra in tumour tissue was found to be linked to a higher fraction of activated immune components, including CD69+ cytotoxic T cells and antigen-presenting HLA-DR+ B cells." (PMID 35301576, 2022). "Indeed, when comparing early- vs late-stage TDLNs, we found that TRM marker CD69 expression was tightly associated with tumor size." (PMID 36229613, 2022). "The expression of CD69 caused retention of tumor-infiltrating CD8 T cells and increased TGFβ production, and these may be the main incentives that induced exhaustion of CD8 T cells." (PMID 34633989, 2021). "These CD103+CD69+CD8+ TRM cells may correspond to truly tumour-reactive T cells the differentiation of which is associated with TGF-β that might be activated in the TME by a mechanism dependent of MMP on tumour cells or αV integrins on immune cells." (PMID 34471106, 2021).